EGFR (epidermal growth factor receptor)
Diseases named in the same sentence as EGFR in open-access papers (continued):
Sharing a sentence is not in itself a finding about the gene and the disease.
tumor (continued). "EGFR inhibition through TKI treatment is known to enhance MHC class I and II antigen presentation, induce more robust infiltration by immune cells and increases local proliferation of T cells in tumors, which leads to increased activation of immune cells and T-cell mediated tumor killing." (PMID 36875137, 2023). "In addition, immune checkpoint inhibitors such as atezolizumab, cemiplimab, and nivolumab plus ipilimumab received FDA approval for treating patients with high PD-L1 expression and no EGFR or ALK genomic tumor aberrations." (PMID 37568193, 2023). "Interestingly, when IHC for EGFR was performed, no expression of the protein was detected on tumor cells." (PMID 38203395, 2023). "A growing number of clinical trials have tried to confirm that EGFR-TKIs combined with angiogenesis inhibitors have superior anti-tumor action than the EGFR-TKIs monotherapy in advanced EGFR-mutant NSCLC, but these studies did not achieve completely consistent results." (PMID 37316870, 2023). "Although the developed PLGA-anti-EGFR FNPs could accumulate in the targeted tumor with enhanced concentration, there still exists nonspecific uptake of nanoparticles throughout the animal body." (PMID 36998445, 2023). "No significant changes in EGFR and Akt expression in the combination treatment group compared to other individual treatment groups in terms of real-time qPCR and immunoblotting of mouse tumor tissues." (PMID 36744262, 2023). "EGFR-modified bacterial minicells loaded with siRNA could validly knock down the expression of PLK1, KSP, CDK1, and have the excellent ability to suppress tumor cell proliferation in HCT116 tumor-bearing mice." (PMID 37896250, 2023). "For example, clinical trials of EGFR and EGFR vIII could be effective for the initial tumor but not responsive in the recurrent one due to its immune evasive trait." (PMID 37046332, 2023). "This can be attributed to the fact that the GE11 peptide itself possesses an insufficient affinity to the EGFR being reflected in an only limited, if not absent, EGFR-specific tumor uptake and an only suboptimal tumor visualization ability of the corresponding imaging agents developed." (PMID 37259420, 2023). "However, one H3-WT tumour without EZHIP overexpression (zcc446) was aneuploid with a high density of single nucleotide and structural variants and lacking either ACVR1 or EGFR mutations." (PMID 36882456, 2023). "Additionally, EGFR-mutant NSCLC patients are generally non-smokers with low levels of PD-L1 expression and tumor mutation burden." (PMID 38001917, 2023). "For example, expressions of HER2, TROP2, EGFR, EpCAM, and nectin 4 are also observed to some extent in non-malignant cells, however because of their overexpression in tumor cells has made them suitable as target antigens in designing ADCs for the solid tumors and currently approved by the FDA." (PMID 37671162, 2023). "In addition, 1G EGFR-TKIs involved gefitinib, erlotinib and icotinib, and EGFR alterations was confirmed by different detection methods, including ARMS-PCR or NGS based on specimens of tumor tissue or plasma samples, and selection bias was inevitable." (PMID 36188595, 2022). "For example, in HPV infection individuals, PD-L1 expression is induced by EGFR and JAK2/signal transducer and activator of transcription 1 (STAT1)-dependent procedures; in particular, inhibition of JAK2 prevents re-regulation of PD-L1 in tumor cells, leading the increased immunologicity." (PMID 37305016, 2022). "In fact, it has been shown that VEGFR-2 inhibition enhances the cytotoxic effect of EGFR inhibitors, whereas, VEGFR-2 activation results in accelerated tumour growth independent of EGFR signalling, thereby facilitating the emergence of resistance to EGFR inhibitors." (PMID 36000167, 2022).
tumor (continued). "In response to EGFR CAR-T cell activation and IFN-γ secretion, the tumor cells upregulated the expression of the intercellular adhesion molecule-1 (ICAM-1), which in turn enabled the progressive entry of EGFR CAR-T cells from the periphery to the center of tumor islets." (PMID 35466279, 2022). "This study focused on the non-enhancing tumor component and showed a significant correlation between the rCBV in the non-enhancing tumor region (NER) and the lack of epidermal growth factor receptor (EGFR) mutation." (PMID 36140526, 2022). "Consequently, innate cell engagers link tumor antigens, such as EGFR, to FcγRIIIa (CD16A) on NK cells or macrophages and activate ADCC and ADCP, resulting in tumor cell killing and phagocytosis of tumor cells, respectively, and potentially the reduction of a tumor mass." (PMID 36185288, 2022). "Tumor-normal and inter-tumor analyses of protein expression data highlighted multiple aberrantly-expressed protein targets in key signaling pathways, including PDGFRB, CDK6, ERBB2, and EGFR whose protein overexpression in HCC tumors are also validated by IHC data from the Human Pathology Atlas." (PMID 35433463, 2022). "We have capitalized on a Drosophila model of cooperative oncogenic transformation that relies on simultaneous overactivation of the EGFR and JAK/STAT signaling pathways (we hereafter refer to this model as EJS) to investigate the functional diversity of caspases during tumor progression." (PMID 35443185, 2022). "Moreover, the use of combination therapy with EGFR, VEGFR, and PDGFR inhibitors together with gemcitabine constitutes promising therapy for pancreatic cancer with strong (80–95%) inhibition of tumor growth and protracted survival in the orthotopic nude mouse model." (PMID 35409206, 2022). "Gefitinib (Iressa, ZD1839), an orally available low molecular weight quinazoline derivative, is an EGFR tyrosine kinase inhibitor (EGFR-TKI) that selectively inhibits the MEK1/2-ERK1/2 cascade by blocking EGFR autophosphorylation and inducing apoptosis of EGF-stimulated tumor cells." (PMID 35892692, 2022). "We confirmed that tumor cells that had been preincubated with cetuximab showed similar binding to the anti-EGFR detection antibody, indicating that both anti-EGFR antibodies bind to different epitopes and therefore do not interfere with each other." (PMID 35035479, 2022). "However, the reason why patients with EGFR-mutated NSCLC harboring preT790M appear to have a poor prognosis has not yet been elucidated, even though the tumor harbors a low-level amount of T790M clones and has undergone surgical resection." (PMID 35840951, 2022). "When combined with gefitinib, metformin can activate the AMPK and epidermal growth factor receptor (EGFR) pathways to synergistically inhibit the growth of BC; when combined with pirubicin, AMPK activation is enhanced, and RNA synthesis is inhibited, which increases tumor suppression." (PMID 36397350, 2022). "For example, if the biopsy result of a tumor shows EGFR-wild type, the result may include false negatives because of intra-tumor heterogeneity." (PMID 35330479, 2022). "EpCAM+EGFR+ events detected in healthy donor blood samples showed no tumor cell-like morphology." (PMID 36613466, 2022). "Growing evidence has revealed that epidermal growth factor receptor (EGFR) is highly expressed in NSCLC cells, and its activation via ligand binding (epithermal growth factor) can induce phosphorylation via tyrosine kinase activity and consequently promote tumor cell proliferation." (PMID 35887373, 2022).
tumor (continued). "Furthermore, biodistribution studies of 111In-ABT-806 (ABT-806i) showed high uptake in tumor, and no binding to normal tissue expressed EGFR, thus confirming the tumor-specific nature of mAb806." (PMID 35326605, 2022). "Although there are many biomarkers closely related to GBM, including insulin-like growth factor 1 (IGF-1), vascular endothelial growth factor (VEGF), isocitrate dehydrogenase 1 (IDH1), and epidermal growth factor receptor (EGFR), no effective tumor markers have been discovered." (PMID 35413821, 2022). "In addition, the phosphorylation of EGFR activates phosphatidylinositol 3-kinase (PI3K), which activates downstream signaling molecules in the pathway and promotes the proliferation, infiltration, and metastasis of tumor cells." (PMID 35190747, 2022). "Taking this into account, we can speculate that the non-functional EGFR fusions could be the by-product of localized genome instability and would thus have no significance in the biology of the tumor." (PMID 36002559, 2022). "Truncated O-glycans frequently found in cancers have been observed to promote tumorigenesis by inducing EGFR and ErbB2 receptor activation and activation of MMP14 that increases the degradation of extracellular matrix (ECM) and initiates tumor growth in mice liver." (PMID 35465326, 2022). "Combining EGFR-targeted PDT with PD-L1 immunotherapy could achieve superior therapeutic efficacy without tumor recurrence." (PMID 36119019, 2022). "Thus, a mechanistic molecular relationship exists between EGFR and LEPRE1 in tumor development." (PMID 35190588, 2022). "Novel tumor specific fluorescent tags, such as labeled antibodies against EGFR, labeled chlorotoxin, and labeled proteoglycan glypican-1 (GPC-1) antibodies may contribute to the identification of infiltrating tumor in the future, but still require additional investigation." (PMID 35624931, 2022). "On the other hand, a high driver-VAF might also indicate the presence of EGFR copy number gain in tumor cells, which would not lead to an increased chance of detecting a putative T790M positive subclone." (PMID 35884570, 2022). "However, further investigation is required to determine how much of the reduction in tumour burden can be attributed to a reduction in Il33 expression, rather than to a direct effect of EGFR inhibition." (PMID 36263033, 2022). "However, with few exceptions, such as EGFR variant III and under‐glycosylated Mucin‐1, the tumour targets in such constructs are not uniquely expressed on cancerous cells and are also found on healthy cell types." (PMID 35908284, 2022). "The phosphorylation levels of EGFR and its downstream proteins were downregulated in the high GTMEIscore group, suggesting that EGFR activation may inhibit the infiltration of immune cells into tumor tissue and that GBM patients with a high GTMEIscore are insensitive to EGFR inhibitors." (PMID 35309323, 2022). "The reason is that the pemetrexed used in group q has an anti-tumor effect, but the therapeutic effect on NSCLC is not obvious, while the osimertinib used in group p has a targeted therapeutic effect on the patients with NSCLC with EGFR gene mutation." (PMID 35757653, 2022). "Since stromal cells can promote tumor growth and influence cancer behavior, we speculated that high expression of USP22 and EGFR suggested a higher degree of stromal cell infiltration in the TME, indicating a worse prognosis, and the K-M curve verified our hypothesis." (PMID 35899194, 2022). "The importance of ICAM-1 expression by the tumor cells was further highlighted by the fact that EGFR-expressing tumor cells at the center of the tumor islets that weakly expressed ICAM-1 were not able to promote EGFR CAR-T cell activation “arrest” within the tumor islets." (PMID 35466279, 2022). "Thus, EGFR pulldown methods provide the means to discern tumor-EVs from EVs secreted by non-tumor cells." (PMID 35795471, 2022).
tumor (continued). "Tumor resistance to FGFRis is identified in multiple tumor types and are mostly related to activation of different signaling pathways including MET, Eph3B, ERBB2/3 or EGFR and/or activation of intracellular signaling pathways without tyrosine kinase receptor dependence." (PMID 35444941, 2022). "Nutritional supplementation with Se/FO could serve as a potential modulator to improve the treatment efficacy of first-generation EGFR-TKI by regulating multiple targets in a non-EGFR mutant NSCLC tumor model." (PMID 36547898, 2022). "Among patients having at least one EGFR-mutant tumor, the demographic parameters were not significantly different between patients having all EGFR-mutant tumors and those having an EGFR-mutant tumor and EGFR-wildtype tumor." (PMID 35740676, 2022). "They used a combination of the A12 (anti-IGF-IR) antibody and cetuximab (anti-EGFR) to simultaneously block EGFR and IGF-IR activation, directly blocking the tumorigenic and angiogenic effects of these receptors, resulting in a significant reduction of tumor volume." (PMID 35956111, 2022). "Importantly, organoids grown from surrounding normal tissues showed lower EGFR expression levels than their tumor counterparts and were not affected by PDT." (PMID 35213974, 2022). "Notably, the activity of EGFR-172 ADC in Raw-ISG-luc cells was >100 fold lower than its activity in THP1-ISG-luc-EGFR cells, suggesting that an ADC taken up by cells through a tumor antigen is more effective at activating the STING pathway than an ADC taken up through an Fc receptor." (PMID 36442099, 2022). "Both the EGFR and IGFR pathways can stimulate metabolic cell modifications in a coordinated way, acting as neoplasm promoters forming a feedback system; evidence portrays that metformin treatment may oppose some of these changes and thus exert antitumor activity." (PMID 35890085, 2022). "Indeed, studies on different components of the tumor microenvironment led to the development of several targeted treatments, such as anti-VEGF, anti-EGFR, or, more recently, anti-PD-1, PD-L1, or CTLA4 antibodies, that considerably improved the prognosis of cancer patients." (PMID 35884357, 2022). "Rather than relying on known signaling pathways, such as EGFR regulated pathways, PaSSS analysis identifies individualized groups of co-varying proteins, deviating in a similar manner from the reference state, in every tumor." (PMID 35154483, 2022). "Upstream RTK regulators (EGFR, HER2, FGFR, cMET, and SHP2), direct mediators of KRAS activation (AURKA), and/or effectors of MAPK and PI3K pathways may escape form KRAS G12C inhibition, with different mechanisms depending on the tumor tissue type." (PMID 35267628, 2022). "Here, the authors identify CRC tumours that are aggressive and prone to early dissemination, characterised by epithelial TGFβ and growth-factor signalling - which could be targeted with MEK/EGFR inhibitors." (PMID 36477656, 2022). "However, the downstream signaling pathway of TRAF4‐mediated EGFR activation, as well as its effects on tumor cells, have not been fully elucidated." (PMID 35748027, 2022). "Previous studies in vivo and in vitro suggested that EGFR might be a therapeutic target also in FOSCC, prompting us to test the anti-cancer potential of Cetuximab in well-characterized cell lines derived from this tumor." (PMID 36467642, 2022). "Collectively, these data warrant investigation into the roles of EGFR in different subtypes of HNSCC to help stratifying patients who are likely to benefit from EGFR-targeted therapy, particularly in HPV-positive tumours, in which inhibition of EGFR could potentially worsen therapy response." (PMID 36333293, 2022). "Previous studies have shown that Epidermal Growth Factor Receptor (EGFR), CD44v (an adhesion molecule expressed in cancer stem-like cells) and OTU deubiquitinase, ubiquitin aldehyde-binding 1 (OTUB1), control and stabilize SCL7A11 expression, facilitating Cys uptake by tumor cells." (PMID 36105219, 2022).
tumor (continued). "When considering results per ethnic subgroup, activating EGFR mutations were detected in 44%, 28% and 14% of non-squamous metastatic NSCLC tumours in Asian, black and white patients, respectively (p = 0.001) and ALK or ROS1 re-arrangement were detected in 22%, 3% and 17%, respectively (p = 0.2)." (PMID 36551542, 2022). "However, a few studies have been conducted at the cell and animal levels, and human tumor xenografts have not shown EGFR-specific concentrations." (PMID 36276079, 2022). "Interestingly, EGFR was found to interact with c-MET and phosphorylate PARP-Y907 in the HCC cells that have high EGFR and c-MET expression, and simultaneous inhibition of both EGFR and c-MET significantly increases the anti-tumor activity of PARPi in such HCC cells." (PMID 36284291, 2022). "Inhibition of Src activity attenuated RSPO2-induced EGFR/Akt phosphorylation, whereas the suppression of Akt activity largely reduced the promotive effect of RSPO2 on cell proliferation, suggesting that RSPO2-induced Src/Akt activation mainly accounts for tumor growth." (PMID 36217544, 2022). "Importantly, EGFR, MET, EPHA2, MAPK1, MAPK3, and RPS6 kinase pathways were strongly dependent on FLCN in RPTEC and also strongly respond to FLCN reconstitution in this BHD tumor cell line, as highlighted in the UOK257 INKA rankings in orange." (PMID 35863698, 2022). "Generally believed, the efficacy of α-PD-1/PD-L1 is modest in EGFR-mutated patients, which might be attributed to the lack of concurrent TIL and PD-L1 expression, low tumor mutation burden, or increased Tregs in the TME." (PMID 35062949, 2022). "Moreover, both in vitro and in vivo trials revealed that inhibition of FGD5-AS1 can release the inhibition of tumor suppressor miR-330-3p, thereby down-regulating the expression of oncogene HK2 and the level of glycolysis and overcoming EGFR-induced 5-fu resistance in rectal cancer cells." (PMID 35475392, 2022). "Early detection of EGFR resistance mechanisms and responses to therapy utilizing non-invasive technology, such as liquid biopsies detecting circulating tumor DNA, may be one tool used in the clinic to monitor these patients." (PMID 35268520, 2022). "In addition, analysis of 22 immune cell types from The Cancer Genome Atlas (TCGA) data showed EGFR L858R was correlated with low level of CD8 T cells, activated CD4 memory T cells and elevated level of macrophage M2 suggesting an inhibited tumor microenvironment (TME)." (PMID 36505399, 2022). "Moreover, long-term tamoxifen treatment has been reported to facilitates the translocation of GPER to cell membranes, resulting in abnormal activation of the EGFR/ERK signaling pathway, which enhances communications between tumor cells and their microenvironment." (PMID 36558071, 2022). "Atezolizumab has been approved as monotherapy for first-line treatment of patients with metastatic NSCLC whose tumors have high PD-L1 expression (either ≥50% of tumor cells or ≥10% of tumor-infiltrating immune cells) and no EGFR alteration or ALK translocation." (PMID 36520426, 2022). "QUESTION: Can EGFR-targeted FMI differentiate between tumor-positive and tumor-negative LNs?" (PMID 34531264, 2022). "The statistical results of western blot and IHC demonstrated that the P-EGFR expression of the cetuximab-treated group was significantly lower than that of the PBS-treated group, matching well with the EGFR activity evaluated by the ETTE probe in tumor tissues." (PMID 35105871, 2022). "Cetuximab (anti-EGFR monoclonal antibody) and bevacizumab (anti-VEGFA monoclonal antibody) enhanced the distribution of the virus in the entire tumor by inhibiting angiogenesis, expanded the number of apoptotic cells, and successfully induced a synergistic anti-tumor effect." (PMID 35371972, 2022). "However, these therapy-related issues related to EGFR do not negate the important role of EGFR signaling in tumor growth and aggressiveness or the clear role of EGFR as a prognostic biomarker for PFS." (PMID 35957892, 2022).